FSHR (follicle stimulating hormone receptor)
Description:
G protein-coupled receptor for follitropin, the follicle-stimulating hormone. Through cAMP production activates the downstream PI3K-AKT and ERK1/ERK2 signaling pathways.
Synonyms: LGR1; FSHRO; FSHR1; ODG1
Tractability: Small molecule: a structure with a bound ligand is known; a high-quality ligand is known; it belongs to a druggable protein family. Antibody: UniProt places it where antibodies can reach, with high confidence; its Gene Ontology location is reachable by antibodies, with high confidence; UniProt predicts a signal peptide or a membrane-spanning region. PROTAC: a small molecule that binds it is known. Other modalities: an approved drug acts on it.
Target class: Membrane receptor; Family A G protein-coupled receptor; Peptide receptor (family A GPCR); Glycohormone receptor
Gene: Protein-coding gene on chromosome 2 (48,962,157 to 49,154,527, reverse strand). Ensembl gene ENSG00000170820.
Subcellular location: Cell membrane
Pathways (Reactome):
Signal Transduction: G alpha (s) signalling events; Hormone ligand-binding receptors
Gene Ontology:
Molecular function: follicle-stimulating hormone receptor activity; protein binding; G protein-coupled peptide receptor activity; G protein-coupled receptor activity; peptide hormone binding; protein-hormone receptor activity; signaling receptor activity
Biological process: cellular response to follicle-stimulating hormone stimulus; follicle-stimulating hormone signaling pathway; G protein-coupled receptor signaling pathway; male gonad development; positive regulation of ERK1 and ERK2 cascade; positive regulation of phosphatidylinositol 3-kinase/protein kinase B signal transduction; adenylate cyclase-activating G protein-coupled receptor signaling pathway; female gamete generation; female gonad development; gonad development; hormone-mediated signaling pathway; ovarian follicle development; spermatogenesis; insulin secretion involved in cellular response to glucose stimulus; response to hormone; transcytosis
Cellular component: membrane; plasma membrane; receptor complex; cell surface; endosome
Genetic constraint (gnomAD): Loss-of-function variants: 44 observed, 52.83 expected, observed/expected ratio (o/e) 0.83, 90% interval 0.65 to 1.07. The synonymous counts are far from expectation, so gnomAD's model fits this gene poorly and the ratio says little. Missense variants: 909 observed, 832.82 expected, observed/expected ratio (o/e) 1.09, 90% interval 1.03 to 1.15. Synonymous variants: 385 observed, 313.27 expected, observed/expected ratio (o/e) 1.23, 90% interval 1.13 to 1.34.
Homologues: Orthologues: chimpanzee FSHR (99% identical), macaque FSHR (97% identical), dog FSHR (91% identical), rabbit FSHR (91% identical), guinea pig FSHR (90% identical), pig FSHR (90% identical), rat Fshr (89% identical), mouse Fshr (87% identical), tropical clawed frog fshr (68% identical), zebrafish fshr (54% identical), Drosophila melanogaster Lgr1 (36% identical), Caenorhabditis elegans fshr-1 (29% identical). Paralogues in human: LHCGR (52% identical), TSHR (49% identical).
Diseases named in the same sentence as FSHR in open-access papers:
FSHR is named in the same sentence as 176 diseases in open-access papers, as found by Europe PMC text mining. Sharing a sentence is not in itself a finding about the gene and the disease. The quoted sentences say what the papers report.
ovarian carcinoma (67 papers, 2011 to 2025). A malignant neoplasm originating from the surface ovarian epithelium. "The ovarian FSH/FSHR axis offers a second potential explanation for the role of remnant follicles in reducing ovarian cancer (OC) risk." (PMID 40722863, 2025). "Another group reported that over-expression of FSHR is associated with development of ovarian epithelial cancer." (PMID 34717703, 2021). "High FSHR or high LHCGR expression in patients with all subtypes of high-grade ovarian cancer was significantly associated with longer progression-free survival (PFS) and overall survival (OS)." (PMID 33374698, 2020). "We showed that higher FSHR and LHCGR expression are associated with early stage, low grade ovarian cancer and that FSHR and LHCGR expression is reduced in HGSOC compared to benign ovarian tumors." (PMID 33374698, 2020). "Investigation into the underlying molecular pathogenesis of ovarian cancer has provided evidence that FSHR activation can influence cancer related gene expression." (PMID 28439256, 2017). "What is most striking about these results is how few of the genes have been previously linked to ovarian cancer, with only follicle stimulating hormone receptor (FSHR) having been previously well studied in ovarian cancer." (PMID 25344116, 2014). "Cox regression analysis confirmed that high FSHR IR score in cancer cells (Relative risk, RR = 0.55, p = 0.035) and FSHR positive blood vessels (RR = 0.40, p = 0.001) were significantly associated with a reduced risk of ovarian cancer death." (PMID 33374698, 2020). "Based on the previous research, we hypothesized that FRBI impacts the expression levels and production of ARID1A, PTEN, and FSHR, which are associated with carcinogenesis and progression of ovarian cancer." (PMID 31241714, 2019). "Elevated FSHR3 (an isoform of FSHR) in OSE has been implicated in ovarian cancers." (PMID 23134576, 2012). "Our study found that, in tumor tissues from 160 patients with different stage of ovarian cancer, the expression of FSHR was found to be correlated with metastasis." (PMID 38505602, 2024). "With the discovery of FSHR in normal ovarian epithelial cells and ovarian cancer cells 4, the role of FSH in the ovarian tumor process induced by abnormal epithelial cell development has progressively attracted research interest." (PMID 38505602, 2024). "We have developed an ovarian cancer-targeted drug delivery system based on a follicle-stimulating hormone receptor (FSHR) peptide." (PMID 38675151, 2024). "Antagonist of gonadotropin 10 and antibodies targeting surface-expressed FSHR 11-13 were shown the potential role of FSHR in ovarian cancer therapy, evident by suppression of tumorigenesis in mouse model of ovarian cancer." (PMID 38505602, 2024). "The FSH receptor (FSHR) is selectively expressed in 50% to 70% of ovarian carcinomas; hence, it is a potential target in treating ovarian tumors." (PMID 37896211, 2023). "The FSHR is involved in pathologies affecting the reproductive tract such as ovarian cancers, infertility, polycystic ovarian syndrome (PCOS), or oligozoospermia." (PMID 37958944, 2023). "The elevated FSH levels of ovarian cancer corroborate with the increased expression of FSHR in several cancers." (PMID 35002517, 2022). "The evaluations carried out on ovarian cancer cells demonstrated the relevance of miR-145 incorporation on a nanosystem structured to achieve better delivery into ovarian cancer cells, taking advantage of the specific presence of FSHR in these types of cells." (PMID 35631544, 2022). "The data obtained on the RI peptide encouraged further developments and optimizations of the molecule for treating ovarian cancers expressing FSHR." (PMID 34445382, 2021).
ovarian carcinoma (continued). "Alternately spliced FSHR isoforms have been reported in clinical samples, ovarian cancers and also on serous ovarian cell lines." (PMID 34717703, 2021). "Multiple isoforms of FSHR have been reported and FSHR has been also expressed on extragonadal tissues including placenta, uterus, prostate, bone tissue and ovarian epithelium as well as ovarian cancer." (PMID 34717708, 2021). "Other groups have also reported FSHR isoforms in mammalian ovaries, human ovarian cancer tissue and cancer cell lines." (PMID 34717703, 2021). "In preclinical studies, it was found that FSHR-targeted CAR T cells specifically kill FSHR+ ovarian cancer cells in vitro and in human ovarian cancer xenograft murine models and patient-derived FSHR+ xenograft models." (PMID 35011583, 2021). "Since cancer involves selective expansion of stem cells, FSHR has been reported on ovarian cancer stem cells." (PMID 34717703, 2021). "A mass spectrometry approach would be useful to confirm and distinguish the different LHCGR and FSHR bands observed in the ovarian cancer cell lines and ovarian tissues." (PMID 33374698, 2020). "This study highlights that lower FSHR and LHCGR expression is associated with a more aggressive epithelial ovarian cancer phenotype and promotes pro-metastatic behaviour." (PMID 33374698, 2020). "We have shown that: (i) high FSHR or LHCGR mRNA expression is associated with early-stage and low-grade ovarian cancer." (PMID 33374698, 2020). "In previous studies, the tumour targets of ovarian cancer-specific fluorescence imaging included folate receptor alpha (FR-α), follicle-stimulating hormone receptor (FSHR), anti–human epidermal growth factor receptor 2 (HER2) and so on." (PMID 32252772, 2020). "We investigated the functional role of gonadotropin receptors in ovarian cancer by knocking down FSHR and LHCGR in OVCAR3 and COV362 cell lines and assessing their effects on cell invasion in vitro." (PMID 33374698, 2020). "An ideal target for ovarian cancer is follicle-stimulating hormone receptor (FSHR) because FSHR expression is mainly limited to ovary tissues and is overexpressed in ovarian cancer." (PMID 33160373, 2020). "Future studies are required to determine if low FSHR enables the heteromer formation with other membrane G protein-coupled receptors and lead to enhanced proliferation in ovarian cancer cells via β-arrestins dependent pathways." (PMID 33374698, 2020). "In this study, FSHR protein bands were seen at ~48 kDa, ~55 kDa and ~65 kDa in the ovarian cancer cell lines and ovarian cancer tissue extracts using the FSHR H-190 antibody." (PMID 33374698, 2020). "We confirmed expression of FSHR in ovary and ovarian cancer cell lines using the FSHR323 antibody by Western blotting." (PMID 33374698, 2020). "Our present results provided a solid foundation for decreasing the progression of ovarian cancer in patients through inhibiting FSHR overexpression in cancer tissues." (PMID 31241714, 2019). "Ovarian cancer patients with high cytoplasmic AhR and concurrent FSHR expression had the worst outcome (median 69.72 vs. 43.32 months; p = 0.043)." (PMID 31212758, 2019). "Our data suggest that AhR and FSHR levels correlate with each other, and their concurrent expression was observed in ovarian cancer patients with the worst outcome." (PMID 31212758, 2019). "In our study, we found that ovarian cancer patients with high cytoplasmic AhR expression have different survival outcomes depending on their FSHR levels." (PMID 31212758, 2019). "FSH exerts its functions via binding to its cognate receptor (FSHR) expressed in ovarian cancers and gynecologic malignancies." (PMID 31241714, 2019). "Studies have indicated FSHR is present at a higher level in the ovarian cancers and gynecologic malignancies." (PMID 29854294, 2018). "This expression pattern makes it possible to use FSHR as the target site against ovarian cancer with high selectivity and specificity." (PMID 29667478, 2018).
ovarian carcinoma (continued). "The distinct hormone molecules and receptors, such as follicle-stimulating hormone receptor (FSHR) in ovarian cancer, provide opportunities for more precisely targeted therapy." (PMID 29461120, 2018). "Then, the plasmids were loaded into a drug delivery system, namely an FSH peptide-conjugated polyethylene glycol (PEG)-polyethylenimine (PEI) copolymer that we previously developed, to target FSHR-expressing ovarian cancer cells." (PMID 29542355, 2018). "FSH β 33-53 peptide-conjugated PAMAM dendrimers also exhibit high selective binding and uptake in FSHR-expressing ovarian cancer cells, ovary and oviduct tissues." (PMID 29461120, 2018). "This vector was specifically delivered into FSHR-expressing ovarian cancer cells through FSH peptide-conjugated nanoparticles." (PMID 29542355, 2018). "The gro-α shRNA-loaded nanoparticles conjugated with FSH peptides in this study showed safe antitumor efficacy in mice with FSHR-positive ovarian cancer." (PMID 29461120, 2018). "An analysis based on TCGA datasets has shown that FSHR is expressed in multiple histological subtypes of ovarian cancer." (PMID 29542355, 2018). "In the present study, we initially examined FSHR expression in five human ovarian cancer cell lines." (PMID 29667478, 2018). "FSHR or GnRHR targeted agents have been developed by using corresponding ligands, and phase II studies have shown their promising applications for ovarian cancer." (PMID 28122595, 2017). "Immunostaining showed that FSHR was overexpressed in the vasculatures of various solid tumors including prostate, breast, lung, and ovarian cancer." (PMID 29097913, 2017). "Several groups have already begun testing FSHR inhibitors for their ability to inhibit the progression of ovarian cancer." (PMID 28439256, 2017). "Further investigation of this novel radiotracer for detection of other FSHR tumor models such as breast and ovarian cancers is currently underway." (PMID 29097913, 2017). "It appears that FSHR not only enhances cell growth but also promotes the invasiveness of ovarian cancer cells." (PMID 28439256, 2017). "Since divergent immunohistochemical findings have been reported for the FSHR protein expression and localization in ovarian cancer and prostate cancer, our goal was to validate FSHR as a drug target in human cancers." (PMID 31548530, 2017). "FSHR acts as an oncogene in ovarian cancer by promoting cell proliferation and survival and antagonizes the tumor suppressing effects of LHR." (PMID 28439256, 2017). "FSH fragments-conjugated polymer or dendrimer based nanomaterials improve drug delivery to ovarian cancer cells by binding to FSHR-positive ovarian cancer cells." (PMID 29097909, 2017). "Recent studies show that the Follicle Stimulating Hormone Receptor (FSHR) is highly expressed on ovarian epithelial cancer cells and facilitates the development and the progression of OC." (PMID 26779384, 2015). "The Follicle-Stimulating Hormone Receptor (FSHR) is used as an imaging biomarker for the detection of ovarian cancer (OC)." (PMID 26779384, 2015). "In some studies, it has been reported that FSHR level can decrease between borderline OETs and ovarian carcinomas." (PMID 26779384, 2015). "In summary, an optical molecular imaging agent was developed a based on the BI-10 deca peptide and demonstrated specific binding to FSHR expressed on ovarian cancer in vitro and in vivo with low affinity." (PMID 26779384, 2015). "FSHR-mediated targeted therapeutics show high potential in ovarian cancer therapy because of limited FSHR distribution in the human reproductive system." (PMID 24252539, 2013). "The neutralizing effect of LH/FSH signalling on GPER-mediated impact on survival was supported by our tissue culture data: ovarian cancer cell proliferation was profoundly reduced when GPER was activated in case of inactivated LH/LHCGR or FSH/FSHR pathways." (PMID 23951246, 2013).
ovarian carcinoma (continued). "Further evidence from three former studies suggests that GnRs exert opposing roles in ovarian cancer with LHCGR being linked to favorable prognosis and FSHR being associated to shorter overall survival." (PMID 23951246, 2013). "We performed in vitro stimulation assay in two out of three GPER positive ovarian cancer cell lines expressing either FSHR or LHCGR." (PMID 23951246, 2013). "To evaluate the possibility of using FSHR and gro-α as therapeutic targets, we examined FSHR and gro-α expression in two human ovarian cancer cell lines." (PMID 24252539, 2013). "This system included follicle-stimulating hormone (FSH) β 33–53 peptide as a targeting moiety that specifically recognized FSH receptor (FSHR) expressed on ovarian cancer cells." (PMID 24252539, 2013). "In a recent study we found an opposed prognostic value of LHCGR and FSHR in ovarian cancer in almost the same panel of patients as described within this study." (PMID 23036050, 2012). "Under the regulation of gonadotropin hormone secreted from the pituitary, ovarian cancers show the high expression of FSHR and LHR on the cellular membrane." (PMID 21617769, 2011). "The team constructed a BiKE that could simultaneously block Siglec-7 on NK cells and target the follicle-stimulating hormone receptor (FSHR) on ovarian cancer cells." (PMID 39911822, 2024). "In addition, chimeric receptors using the entire FSH subunit can effectively redirect the cytotoxic activity of T cells against various patient-derived FSHR+ ovarian carcinomas." (PMID 39741875, 2024). "Follicle-stimulating hormone receptor (FSHR) expression is limited to the reproductive system and might be targeted to deliver drugs against ovarian cancer with high selectivity and specificity." (PMID 34445382, 2021). "Additionally, the expression levels of both phospho-SphK1 and phospho-SphK2 were closely correlated with the expression level of follicle-stimulating hormone receptor (FSHR) in ovarian cancer tissues." (PMID 32796926, 2020). "The findings in this study agree with previous studies demonstrating decreased FSHR mRNA and FSHR protein expression with increasing clinical stage and progression from borderline tumors to ovarian carcinomas and higher FSHR expression in low grade tumors compared to grade III tumors." (PMID 33374698, 2020). "Together, our findings support the hypothesis that reduced FSHR and/or LHCGR is associated with a poorer prognosis and can promote pro-metastatic ovarian cancer cell behaviour." (PMID 33374698, 2020). "This study investigated whether FSHR and LHCGR mRNA and protein levels are associated with ovarian cancer progression and if the knockdown of these gonadotrophin receptors affects invasive behavior of serous ovarian cancer cells in vitro." (PMID 33374698, 2020). "Furthermore, using the Kaplan–Meier online plotter we showed that high FSHR expression was linked with increased PFS and OS in all ovarian cancer patients and patients with high grade disease." (PMID 33374698, 2020). "Ovarian cancer patients with high levels of AhR and FSHR could potentially benefit from treatment with gonadotropin-releasing hormone (GnRH) agonists/antagonists." (PMID 31212758, 2019). "However, the examination of both AhR and FSHR revealed that AhR staining intensity is strongly correlated with FSHR expression in the ovarian cancer specimens." (PMID 31212758, 2019). "FSHR stimulation upregulated Oct4 expression via the Erk1/2 pathway in epithelial ovarian cancer." (PMID 30941099, 2019). "Endothelial FSHR was detected by immunohistochemical and immunoblotting analysis in samples obtained from >1,000 patients with breast, prostate, colon, pancreas, urinary bladder, kidney, lung, liver, stomach, testis, and ovarian cancer." (PMID 30941099, 2019). "Furthermore, our study revealed a strong correlation between (cytoplasmic) AhR and FSHR in ovarian cancer patients." (PMID 31212758, 2019).